LEPR (leptin receptor)
Diseases named in the same sentence as LEPR in open-access papers (continued):
Sharing a sentence is not in itself a finding about the gene and the disease.
ovarian carcinoma (17 papers, 2009 to 2023). A malignant neoplasm originating from the surface ovarian epithelium. "Leptin has been reported to induce proliferation of ovarian cancer cells in vitro and overexpression of leptin receptor has been linked to unfavorable prognosis in ovarian cancer patients." (PMID 25026276, 2014). "In clinical, leptin and leptin receptor serves as poor prognostic markers in variant types of cancer including ovarian cancer, colon cancer, AML, gastric cancer, while the prediction of good outcome by the same axis has also been observed in soft tissue cancer." (PMID 29682217, 2018). "LEPR was found to be overexpressed in epithelial ovarian cancer indicating poor progression-free survival and its somatic mutation was found to increase the susceptibility to hepatocarcinogenesis." (PMID 36816023, 2023). "The study showed that leptin stimulation led to an increased proliferation, survival and migration of LEPR-expressing ovarian cancer cell lines, with these effects shown to be mediated by the JAK2/ STAT3 pathway." (PMID 37238197, 2023). "A cohort study enrolling ovarian cancer patients indicated a significant correlation of leptin and leptin receptor coexpression with shorter survival time." (PMID 33799880, 2021). "A study in ovarian cancer cohort significantly showed the correlation of leptin and leptin receptor co-expression with shorter patient survival." (PMID 29682217, 2018). "Our previously published results concerning the action of leptin receptor antagonists on epithelial ovarian cancer cells showed that both antagonists studied decreased cdk2 and cdk4 protein expression in CaOV-3 and OVCAR-3 cells." (PMID 28861689, 2017). "This was consistent with high co-expression of LEP and LEPR correlating with poor survival of ovarian cancer patients." (PMID 29212170, 2017). "Both inhibitors were able to suppress leptin-mediated proliferation, survival and migration in LEPR-expressing ovarian cancer cells." (PMID 29212170, 2017). "The role of leptin in tumorigenesis was suggested by the high expression of the leptin receptor (ObR) in several cancer cells, such as breast, stomach, colon, ovarian cancers and leukemia." (PMID 28915700, 2017). "Further analysis revealed that high co-expression of leptin and LEPR correlated with reduced survival in ovarian cancer patients." (PMID 29212170, 2017). "Analysis of ovarian cancer cell lines expressing functional LEPR revealed that leptin induced proliferation of adenocarcinoma cell lines and stimulated both survival and migration in both adenocarcinoma and teratocarcinoma cell types." (PMID 29212170, 2017). "This study identified leptin-induced migration of LEPR-positive ovarian cancer cells mediated via JAK2/STAT3." (PMID 29212170, 2017). "Future studies should be carried out using explants from patients with ovarian cancer and then validated in in vivo models, which would allow the investigation of the effects of leptin receptor antagonists on living organisms." (PMID 27480179, 2016). "Recent studies have suggested that higher circulating levels of leptin, higher leptin receptor expression by the tumor and a high leptin to adiponectin (L:A) ratio all correlate with a worse outcome in several epithelial cancers, including ovarian cancer." (PMID 26053184, 2015). "Moreover, by using specific leptin receptor antagonists, they found that these compounds were able to inhibit the leptin-induced proliferation of ovarian cancer cells." (PMID 37509120, 2023). "Moreover, the blockade of the leptin receptor has been demonstrated to inhibit tumor progression through the diffusion of ovarian cancer cells in the peritoneal cavity in an animal model." (PMID 34440886, 2021). "These factors have led us to investigate the role of LEPR signaling in ovarian cancer." (PMID 29212170, 2017).
ovarian carcinoma (continued). "Leptin stimulation led to increased proliferation, survival and migration of LEPR-expressing ovarian cancer cell lines, with the effects shown to be mediated by the downstream Janus kinase 2/Signal transducer and activator of transcription 3 (JAK2/STAT3) pathway." (PMID 29212170, 2017). "Furthermore, high co-expression of LEP and LEPR within the tumor clearly represented a poor prognostic factor for epithelial ovarian cancer, consistent with another recent study." (PMID 29212170, 2017). "This study collectively suggests that leptin/LEPR signaling via JAK2/STAT3 has the potential to significantly impact on pathogenesis in a subset of ovarian cancer patients who may benefit from strategies that dampen this pathway." (PMID 29212170, 2017). "Preliminary experiments revealed vastly different levels of LEPR expression in a group of Grade 3 ovarian tumors that was confirmed in a panel of 52 cell lines representing a range of different ovarian cell sub-types and in 484 ovarian cancer samples." (PMID 29212170, 2017). "This study investigated a potential role for LEPR signaling in ovarian cancer." (PMID 29212170, 2017). "We first examined whether the human ovarian cancer cell lines and the primary tissue cultures expressed the active isoform of the leptin receptor, OB-Rb." (PMID 26053184, 2015). "Taken together, our results demonstrate that leptin mediates the aggressiveness of epithelial cancer and offer an explanation as to why ovarian cancer patients with higher circulating serum leptin levels or leptin receptor-expressing tumors experience a worse survival rate." (PMID 26053184, 2015). "Clinically, enhanced expression of LEPR was observed in human oesophageal, breast, gastric, colon and gastric cancer tissues and could predict cancer progression in bladder, endometrial and ovarian cancer." (PMID 33397392, 2021). "In addition, leptin receptor is relatively high expressed in kidney cancer, liver cancer, lung cancer, mesothelioma, ovarian cancer, pancreatic cancer, prostate cancer, sarcoma, thyroid cancer and acute myeloid leukemia, indicating the potential pathological role of this axis in cancers." (PMID 29682217, 2018). "Therefore, the potential role of LEPR signaling in ovarian cancer biology was investigated." (PMID 29212170, 2017). "The overexpression of histone deacetylases (HDACs) was known to elicit carcinogenesis, and leptin receptor antagonists, SHLA and Lan2, were shown to eliminate the effect induced by leptin in ovarian cancer." (PMID 33799880, 2021). "However, whether LEPR-mediated signaling impacted on ovarian cancer remained poorly understood." (PMID 29212170, 2017). "The leptin receptor shares structural homology with other cytokine family members, including IL-6, which is known to be involved in the EMT of ovarian cancer cells." (PMID 26053184, 2015). "A role for leptin/LEPR in the survival of ovarian cancer cells was also demonstrated, similarly through the JAK2/STAT3 pathway, consistent with a previous study showing an alternate JAK2 inhibitor was able to induce apoptosis in ovarian cancer cells." (PMID 29212170, 2017). "The main aim of this study was to determine the possible use of the leptin receptor blockers superactive human leptin antagonist (SHLA) and quadruple leptin mutein, Lan-2 (L39A/D40A/F41A/I42A), as additional therapy factors for the treatment of ovarian cancer." (PMID 27480179, 2016). "By plotting the putative copy-number alterations (CNA) and mRNA expression levels for LEP and LEPR, we found that the upregulation or amplification of the LEP gene in ovarian cancer correlates with a slight increase in the LEP mRNA levels in the samples analyzed by RNA Seq V2 in the TCGA database." (PMID 26053184, 2015). "Moreover, folliculoma is not well studied among the ovarian cancer types, although both the short (ObRa) and long (ObRb) forms of the leptin receptor are present in human granulosa cells." (PMID 28861689, 2017).
endometrial cancer (16 papers, 2013 to 2026). Primary or metastatic malignant neoplasm involving the endometrium (mucous membrane that lines the endometrial cavity). "In regard to the association of leptin receptor and endometrial carcinoma, Sharma, and associates (2006) found that leptin treatment resulted in the increase of type-I Ishikawa/ECC1 endometrial carcinoma cells that respond to the hormone." (PMID 37600567, 2023). "Also, the serum level of leptin should be investigated and the diagnostic accuracy of leptin receptor in the endometrial cancer should be determined based on the R.O.C (Receiver Operating Characteristics) curve and the cut point." (PMID 37600567, 2023). "The leptin receptor may be a risk factor for the endometrial carcinoma, which was found among the evaluated women in Kashan." (PMID 37600567, 2023). "The leptin receptor may be a risk factor for the endometrial carcinoma among women tested in Kashan." (PMID 37600567, 2023). "Furthermore, the results of a correlation analysis in an endometrial cancer cohort demonstrated the positive association of lymph node metastasis with high leptin and leptin receptor levels." (PMID 33804101, 2021). "Notably, one study showed that downregulation of the short form of LEPR was significantly associated with poor tumor differentiation in endometrial cancer." (PMID 32046756, 2020). "Based on these results, leptin receptor should be considered as a potential biomarker for the endometrial carcinoma screening or targeting the therapeutic purposes." (PMID 37600567, 2023). "The results demonstrated that LEPR expression was significantly altered in all grades of endometrial cancer compared to control in both tissue and whole blood samples." (PMID 34202922, 2021). "Leptin receptor modulation promotes the development of endometrial cancer through the activation of JAK2/STAT3, MAPK/ERK, PI3K/AKT and COX-2 signaling pathways." (PMID 33799622, 2021). "Recent studies have found that abnormal expression of leptin and leptin receptor signaling related to obesity plays an important role in the development of breast, colon and endometrial cancer." (PMID 31440472, 2019). "Based on these results, leptin receptor might be considered as a potential biomarker for screening the endometrial carcinoma or targeting the therapeutic purposes." (PMID 37600567, 2023). "The aim of this study was to analyze the frequencies of genotypes and alleles of Single Nucleotide Polymorphism (SNP) LEP-R c.668A>G (p.Gln223Arg, rs1137101) of leptin receptor gene and to assess the influence this DNA marker has on endometrial cancer (EC) with respect to total body fat content." (PMID 34399708, 2021). "On the other hand, LEPR showed a significant increase in all three grades of endometrial cancer." (PMID 34202922, 2021). "In endometrial cancer, although LEP and LEPR were more highly expressed in endometrial tumor tissues than normal tissues, there was a suggestion that rates of LEPR positivity were significantly lower among poorly differentiated endometrial tumors." (PMID 32046756, 2020). "This study was aimed to compare the leptin receptor (Ob-R) expression in the endometrial carcinoma cases and non-carcinoma samples." (PMID 37600567, 2023). "In this study, the expression of leptin receptor was examined in the endometrial carcinoma and non-carcinoma samples." (PMID 37600567, 2023). "Therefore, this research was designed to compare the leptin receptor expression in the endometrial carcinoma versus the non-cancer lesions of endometrium and normal tissue." (PMID 37600567, 2023).
depression (14 papers, 2014 to 2025). "The top three genes of the module, YOD1, RBX1, and LEPR, have been shown previously to be associated with neurodegenerative diseases, bipolar disorder, and depression." (PMID 38726387, 2024). "Some individuals with POMC or LEPR deficiency experienced mild-to-moderate depression at the time of trial enrollment." (PMID 35123544, 2022). "The leptin receptor (LEPR) regulates synapses, neuronal plasticity, cognition, and cortical volume, and has been associated with memory maintenance and depression." (PMID 35159365, 2022). "In addition, the deletion of leptin receptor (LepRb) and its downregulation are associated with depression-like behavioral impairments, indicating that leptin-lepRb signaling is involved in the molecular mechanism of leptin antidepressant action." (PMID 33066277, 2020). "Leptin signaling is involved in the pathophysiology of major depressive disorders, exerting its effects by activation the leptin receptor, which is distributed in various brain regions such as the prefrontal cortex and hippocampus, two limbic brain areas implicated in depression." (PMID 29186207, 2017). "As for the ZDF rats, the depression condition may be worse because they are genetically deficient in leptin receptor and are resistant to leptin, which is an adipocyte-derived hormone with antidepressant-like properties." (PMID 25347185, 2014). "Here, we show that the leptin receptor (LepRb) colocalizes with brain-derived neurotrophic factor (BDNF), a key player in the pathophysiology of major depression and the action of antidepressants, in the dentate gyrus of the hippocampus." (PMID 33106599, 2021). "Among other receptors, platelets express on their surface also receptors for peptide hormones, including the long form of leptin receptor (LEPRL), suggesting that alteration of leptin levels occurring in depressive disorders may alter platelet response contributing to cardiovascular complications." (PMID 33066277, 2020).
colorectal cancer (13 papers, 2010 to 2025). A primary or metastatic malignant neoplasm that affects the colon or rectum. "Similar trends have been demonstrated between soluble leptin receptor and risk of colorectal cancer." (PMID 40902078, 2025). "We examined the relevance of genetic variants of LEP and leptin receptor (LEPR) to colorectal cancer (CRC) survival by using data from the Newfoundland Familial Colorectal Cancer Study." (PMID 37282602, 2023). "A recent colorectal cancer case–control study related to polymorphisms revealed the association of LEPR rs6588147 and rs1137101, as well as LEP rs2167270, with lower cancer risk, whereas LEPR rs1137100 was associated with cancer susceptibility." (PMID 35563103, 2022). "A study of colorectal cancer showed that downregulation of LEPR IHC expression was associated with aggressive tumor features (namely late stage, high grade) as well as with shorter survival time." (PMID 32046756, 2020). "Cumulative effect of risk factors of smoking, family history of cancer, LEPR rs12037879, and rs6690625 in colorectal cancer susceptibility in combined study." (PMID 23593308, 2013). "In the first stage, the LEPR rs12037879 G/A polymorphism was associated with marginally increased colorectal cancer risk, with ORs of 1.34 (95%CI: 1.01–1.80) and 1.40 (95%CI: 1.06–1.85) for GA vs GG and GA+AA vs GG, respectively." (PMID 23593308, 2013). "In the main-effect analysis, LEPR rs12037879 exhibited marginal association with increased colorectal cancer risk in combined population." (PMID 23593308, 2013). "LEPR rs12037879 only presented modestly increased colorectal cancer risk, with odds ratios of 1.41 (95% confidence interval [CI] 1.13–1.76) and 1.74 (95%CI 1.08–2.81) for GA and AA genotype when compared with GG genotype in combined population." (PMID 23593308, 2013). "Additionally, in Chinese populations, previous studies reported that rs6588147 locus in LEPR gene was associate with a lower susceptibility of colorectal cancer and hepatocellular carcinoma." (PMID 38659416, 2024). "Interestingly, overexpression of LEPR in colorectal cancer was associated with an increase in metastatic potential and enhanced neoangiogenesis." (PMID 34202922, 2021). "In conclusion, we provide evidence that one SNP in LEPR (rs12037879) may be associated with a marginal increase in colorectal cancer risk." (PMID 23593308, 2013). "Therefore, we performed a two-stage case-control study to systemically evaluate single nucleotide polymorphisms (SNPs) of LEP and LEPR as a predictor of colorectal cancer risk in Chinese population." (PMID 23593308, 2013). "Multifactor gene-environment interaction analysis revealed significant interactions among LEPR rs12037879, LEPR rs6690625, smoking status and family history of cancer, exhibiting a gradient of increased colorectal cancer risk along with the increasing number of risk factors (P = 9.82×10−10)." (PMID 23593308, 2013). "We found that LEPR rs12037879 was associated with a marginal increase in colorectal cancer risk." (PMID 23593308, 2013). "Our research supports that polymorphisms in LEPR may be associated with marginal increase in the risk for colorectal cancer." (PMID 23593308, 2013). "Polymorphism of adipokine genes such as LEPR can increase the risk of colorectal cancer." (PMID 20187943, 2010). "Aim of the Paper: The aim of the study was to assess the concentration of leptin in the blood serum as well as the expression of the leptin receptor in colorectal cancer cells." (PMID 36981858, 2023). "The aim of the study was to assess the concentration of leptin in the blood serum as well as the expression of the leptin receptor in colorectal cancer cells." (PMID 36981858, 2023). "The critical role of leptin receptor expression in the proliferation of colorectal carcinoma has also been evaluated in the clinic." (PMID 33799880, 2021).
colorectal cancer (continued). "In a cohort study of 75 colorectal carcinoma patients, elevated LEPR expression was accompanied by the observation of neoangiogenesis and an increase in metastatic potential." (PMID 33799880, 2021). "In this study, we have investigated the degree of expression of LEP and LEPR in colorectal cancer (CRC)." (PMID 31592340, 2019). "In colorectal carcinoma, relative leptin receptor level displayed the correlation with cancer cell proliferation and neoangiogenesis." (PMID 29682217, 2018). "Leptin receptor expression occurs in many cancer cells, including colorectal cancer cells." (PMID 36981858, 2023). "In a colorectal cancer cohort of 1003 cases and 1303 matched controls, LEPR rs6588147, rs1137101, and LEP rs2167270 polymorphisms were found to be associated with a decrease in cancer risk, whereas LEPR rs1137100 was associated with cancer susceptibility." (PMID 33799880, 2021). "In this study, we graded staining as ‘negative,’ ’low,’ and ’high’ (as elaborated in methodology) and observed presence of both LEP and LEPR in colorectal cancer (CRC) tissue samples in high intensity with high prevalence, 100% and 97.7% respectively (p < 0.01)." (PMID 31592340, 2019). "In 92% of the colorectal carcinoma cases with pronounced leptin receptor expression, high rate of angiogenesis case was observed alone with the correlation of low grade neoangiogenesis and leptin receptor absence (88.2% of the cases)." (PMID 29682217, 2018). "Smokers carrying LEPR rs12037879 A allele presented 1.67-fold (95%CI 1.39-fold to 2.01-fold) increased colorectal cancer risk when compared with non-smokers carrying GG genotype in combined analysis." (PMID 23593308, 2013). "Individuals with family history of cancer harboring LEPR rs12037879 A allele showed 1.52-fold (95%CI: 1.24-fold to 1.86-fold) increased colorectal cancer risk, compared with individuals without family history of cancer harboring GG genotype." (PMID 23593308, 2013). "Moreover, LEPR was significantly overexpressed in human colorectal cancer than normal colonic mucosa, and positively related with the expression of hypoxia-inducible factor 1, a proneoplastic transcriptional regulator, which caused a more advanced tumor phenotype." (PMID 23593308, 2013). "Moreover, LEPR expression plays an essential role in colorectal carcinoma proliferation processes, whereby a lack of LEPR expression decreased tumor proliferation in most colorectal carcinoma cases, while high levels of expression resulted in neoangiogenesis and increased metastatic potential." (PMID 35563103, 2022).